H3C8 (H3 clustered histone 8)
Description:
Core component of nucleosome. Nucleosomes wrap and compact DNA into chromatin, limiting DNA accessibility to the cellular machineries which require DNA as a template. Histones thereby play a central role in transcription regulation, DNA repair, DNA replication and chromosomal stability. DNA accessibility is regulated via a complex set of post-translational modifications of histones, also called histone code, and nucleosome remodeling.
Synonyms: H3FH; HIST1H3G; H3/h
Gene: Protein-coding gene on chromosome 6 (26,270,918 to 26,271,413, reverse strand). Ensembl gene ENSG00000273983.
Subcellular location: Nucleus; Chromosome
Subcellular location (Human Protein Atlas): Nucleoplasm
Pathways (Reactome):
Gene expression (Transcription): B-WICH complex positively regulates rRNA expression; DNA methylation; ERCC6 (CSB) and EHMT2 (G9a) positively regulate rRNA expression; MLL4 and MLL3 complexes regulate expression of PPARG target genes in adipogenesis and hepatic steatosis; NoRC negatively regulates rRNA expression; PRC2 methylates histones and DNA; RNA Polymerase I Promoter Escape; RNA Polymerase I Promoter Opening; RUNX1 regulates genes involved in megakaryocyte differentiation and platelet function; RUNX1 regulates transcription of genes involved in differentiation of HSCs; Regulation of endogenous retroelements by KRAB-ZFP proteins; Regulation of endogenous retroelements by Piwi-interacting RNAs (piRNAs); Regulation of endogenous retroelements by the Human Silencing Hub (HUSH) complex; SIRT1 negatively regulates rRNA expression; Transcriptional regulation by small RNAs
Chromatin organization: CHD1 and CHD2 subfamily; CHD6, CHD7, CHD8, CHD9 subfamily; ChAHP complex assembly; Chromatin modifying enzymes; HATs acetylate histones; HDACs deacetylate histones; HDMs demethylate histones; Interaction of NuRD complexes with transcription factors; NuRD complex assembly; PKMTs methylate histone lysines; RMTs methylate histone arginines
Disease: Defective pyroptosis; Dengue Virus-Host Interactions; HCMV Early Events; HCMV Late Events
Signal Transduction: Activated PKN1 stimulates transcription of AR (androgen receptor) regulated genes KLK2 and KLK3; Estrogen-dependent gene expression; Formation of the beta-catenin:TCF transactivating complex; Pre-NOTCH Transcription and Translation
Developmental Biology: Activation of anterior HOX genes in hindbrain development during early embryogenesis; Chromatin modifications during the maternal to zygotic transition (MZT); Transcriptional regulation of granulopoiesis
Immune System: FXIIa activates plasma kallikrein-kinin system; Interleukin-7 signaling; Regulation of PD-L1(CD274) transcription
and 8 more pathways
Gene Ontology:
Molecular function: cadherin binding; protein binding; structural constituent of chromatin; nucleosomal DNA binding; DNA binding; protein heterodimerization activity
Biological process: epigenetic regulation of gene expression; nucleosome assembly; chromatin organization; heterochromatin formation; telomere organization
Cellular component: chromatin; extracellular exosome; membrane; nucleoplasm; nucleosome; nucleus; protein-containing complex; extracellular region; chromosome
Genetic constraint (gnomAD): Loss-of-function variants: 15 observed, 8.34 expected, observed/expected ratio (o/e) 1.8, 90% interval 1.12 to 1.96. That is too few expected variants to judge how well the gene tolerates losing a copy. Missense variants: 230 observed, 207.13 expected, observed/expected ratio (o/e) 1.11, 90% interval 1 to 1.24. Synonymous variants: 143 observed, 83.57 expected, observed/expected ratio (o/e) 1.71, 90% interval 1.49 to 1.93.
Homologues: Orthologues: chimpanzee H3C11 (100% identical), dog H3C8 (100% identical), macaque H3C11 (100% identical), Drosophila melanogaster His3:CG33812 (99% identical), zebrafish si:ch1073-153i20.2 (99% identical), zebrafish si:ch211-113a14.20 (99% identical), zebrafish si:ch211-113a14.23 (99% identical), zebrafish si:ch211-113a14.27 (99% identical), zebrafish zgc:173552 (99% identical), Caenorhabditis elegans his-17 (97% identical), Caenorhabditis elegans his-2 (97% identical), Caenorhabditis elegans his-32 (97% identical), and 8 more. Paralogues in human: H3C1 (100% identical), H3C10 (100% identical), H3C11 (100% identical), H3C12 (100% identical), H3C2 (100% identical), H3C3 (100% identical), H3C4 (100% identical), H3C6 (100% identical), H3C7 (100% identical), H3C13 (99% identical), H3C14 (99% identical), H3C15 (99% identical), and 8 more.